CDK1 (cyclin dependent kinase 1)
Diseases named in the same sentence as CDK1 in open-access papers (continued):
Sharing a sentence is not in itself a finding about the gene and the disease.
tumor (continued). "Moreover, in malignant tumor cells, the altered expression of CDK1 and its regulators can lead to uncontrolled CDK1 activity, which can cause uncontrolled proliferation of tumor cells and aggravate the malignancy of the tumor." (PMID 36090896, 2022). "Further analysis indicated that CDK1 may influence tumor immunity mainly by mediating the degree of tumor infiltration of immune-associated cells, and the effect of CDK1 on immunity is diverse across tumor types in tumor microenvironment." (PMID 36090896, 2022). "Moreover, overexpression of CDK1 could weaken the tumor suppressive effect caused by CDCA8 knockdown." (PMID 35517403, 2022). "Therefore, over-expression of the cdk1-cyclin B axis seems to contribute to the aggressive tumor regrowth caused by temsirolimus resistance and, consequently, this axis may provide a pivotal therapeutic target in counteracting resistance." (PMID 31010254, 2019). "In a previous study, we demonstrated that brachyury-mediated immune resistance associates with decreased levels of the cyclin-dependent kinase 1 (CDK1) protein, and that reconstitution of CDK1 levels could restore the tumor cells’ susceptibility to immune effector cells." (PMID 29774202, 2018). "To investigate a potential association between the loss of CDK1 protein and reduction of p21, here, we have conducted co-immunoprecipitation assays using an anti-CDK1 antibody to investigate whether these two proteins could be associated in tumor cells with high vs. low brachyury levels." (PMID 29774202, 2018). "Cyclin-dependent kinases (CDKs), especially CDK-2 and CDK-1, are essential for regulating the cell cycle, cell growth, and tumor genesis." (PMID 41965404, 2026). "IL-6 and B-cell lymphoma 2 showed downregulated expression in tumor tissues, while cyclin-dependent kinase 1, cyclin-dependent kinase 2, cyclin B1, Erb-B2 receptor tyrosine kinase 2, and cyclin B2 were upregulated." (PMID 41650055, 2026). "We have verified that AS/BJO-NEs can play an anti-tumor role by down-regulating CDK1 and subsequently reducing the expression of MTFR2, as well as inhibiting the proliferation, migration and invasion capabilities of OSCC cells and the EMT process." (PMID 40748969, 2025). "Beyond this well-known role, the CCNB1/CDK1 complex also influences tumor-related signaling pathways." (PMID 40430484, 2025). "In normal tissues, the expression of CDK1 is concentrated in a lower range, while the expression in tumor tissues is upregulated." (PMID 41278293, 2025). "The expressionof BCL2, which is decreased in tumor hepatocytes, canbe suppressed by four proteins (CDK1, VDAC1, MMP9,CYC), the expression of which is increased in malignant hepatocytes compared with hepatocytes from healthy livertissue." (PMID 41541554, 2025). "Here, the authors identify that CCNE1-amplified gynecological cancer is sensitive to combined PKMYT1 and ATR inhibition via CDK1 activation, resulting in premature mitosis, DNA damage, cell apoptosis and reduced tumour growth and metastasis." (PMID 40169546, 2025). "Numerous studies have demonstrated that CDK1 dysregulation leads to chromosomal instability, aggressive tumor growth, and accelerated cell proliferation." (PMID 40657363, 2025). "Monitoring of CDK1 mRNA levels by real-time quantitative PCR technology can provide clinicians with real-time information about tumor progression and treatment response, thus achieving more precise treatment regimen adjustments." (PMID 40332418, 2025). "The dynamic changes in CDK1 expression and its relationship with tumor heterogeneity also require further studies to clarify the tumor heterogeneity." (PMID 40332418, 2025).
tumor (continued). "Further, UALCAN protein expression analysis demonstrated that CDK1 protein levels were elevated across all tumor stages relative to normal samples." (PMID 40748969, 2025). "Overexpression of CDK1 is observed in several tumour types, yet the control of CDK1 expression levels is poorly understood." (PMID 40518827, 2025). "Paired analysis further demonstrated the expression differences between normal and tumor tissues in each pair of samples, with CDK1 expression generally higher in tumor samples." (PMID 41278293, 2025). "A network of interacting proteins was assembled to determine hub genes, and TOP2A and CDK1 were selected for immunohistochemical (IHC) validation in 76 SCCE tumor samples." (PMID 40765849, 2025). "Utilizing cationic lipid-assisted poly(ethylene glycol)-block-poly(d,l-lactide) (PEG5K-PLA11K) nanoparticles for the delivery of CDK1-specific siRNA has shown potential in inhibiting tumor growth by effectively silencing CDK1 expression." (PMID 40573996, 2025). "Based on these mechanisms, targeted inhibition strategies against key nodes in DDR pathways (such as CHK1/CDK1) and the CSCs microenvironment offer novel therapeutic approaches for overcoming tumor resistance." (PMID 41473689, 2025). "Dinaciclib (also known as MK-7965 and SCH727965) is a cyclin-dependent kinase (CDK1/2/5/9) inhibitor that controls cell-cycle progression and induces apoptosis in different tumor cells." (PMID 40264756, 2025). "In conclusion, this study provides strong evidence that curcumin exerts its anticancer effects in CRC by modulating the miR-134-5p/CDCA3/CDK1 axis, thereby suppressing tumor cell proliferation and invasion and promoting apoptosis." (PMID 40969596, 2025). "For instance, in an HCC patient-derived xenograft (PDX) tumor model, treatment with the CDK1 inhibitor RO3306 in combination with sorafenib significantly decreased tumor growth." (PMID 40657363, 2025). "This cell cycle blockade correlated with the observed reduction in CDK1 protein levels, strongly suggesting that PAB’s anti-tumor activity is mediated, at least in part, through CDK1-related inhibition of G2/M progression." (PMID 41142571, 2025). "CDK1 expression was evaluated across three tumor-derived cell lines representing different tissue origins." (PMID 41009727, 2025). "Overexpression of CDK1 mRNA and protein has been frequently observed in tumor tissues, potentially driven by gene amplification or activation of upstream transcriptional regulators such as E2F1 and FOXM1." (PMID 41009727, 2025). "Transcriptional analysis showed a marked downregulation of key genes involved in tumor cell growth and proliferation, including CDK1, CDK2, and CDK6 (up to a 31.11‐fold decrease), PLK1 (up to a 21.49‐fold decrease), and SKP2 (up to a 14.68‐fold decrease)." (PMID 41221154, 2025). "Existing research has demonstrated that during the cell cycle, CDK1 holds a crucial regulatory role in mitochondrial function and can influence the proliferation and apoptosis of tumor cells by modulating mitochondrial bioenergetics." (PMID 40748969, 2025). "Our findings reveal a tumor-specific mechanism in which CDK1 reprograms LDH isoenzyme composition to direct lactate toward NADH production, ensuring energy homeostasis during mitosis." (PMID 40940446, 2025). "Second, the anti-tumor effects of CCNB1/CDK1 inhibition extend beyond PD-L1 regulation, including modulation of the IL-6-JAK-STAT3 axis and TGF-β signaling." (PMID 40430484, 2025).
tumor (continued). "The mitochondrial relocation of CCNB1/CDK1 enhances the ATP production needed for DNA damage repair, aiding cell survival and contributing to tumor resistance to DNA-damaging treatments such as chemotherapy and radiotherapy." (PMID 40675964, 2025). "Elevated CDK1 expression correlated with reduced overall survival (HR = 2.41, 95% CI:1.78–3.26, p = 0.003) and advanced tumor staging (p = 0.007)." (PMID 40332418, 2025). "Each of the four genes (HJURP, CDK1, FOXM1, and CHEK1) identified in the model has been implicated in cell cycle regulation and tumor development." (PMID 40299539, 2025). "Many studies inhibiting tumor proliferation by targeting CDK1 have obtained meaningful results—for instance, miR-181a inhibits cell proliferation by regulating the expression of CDK1 in NSCLC cells." (PMID 40040723, 2025). "This suggests that CDK1 promotes tumor growth primarily through sustaining AKT activation and maintaining the cell cycle machinery." (PMID 41278293, 2025). "Alsterpaullone selectively inhibits cyclin-dependent kinases (cdk1) (IC50s = 0.035 μM)and retard tumor growth." (PMID 40546347, 2025). "In tumor cells CDK1 phosphorylates numerous oncogene and tumor suppressor proteins, and several upstream modulators can positively or negatively influence CDK1 activation, amplification, transcription, and expression." (PMID 39800748, 2025). "Immunofluorescence analysis revealed prominent CDK1 protein expression in the nucleoplasm and cytosol of human epithelial tumor cells." (PMID 41009727, 2025). "We then used ROC curves to evaluate the predictive performance of CDK1 in tumor diagnosis and found that CDK1 showed a high classification ability with an AUC up to 0.978." (PMID 41278293, 2025). "During the G2/M phase, the diphosphatase CDC25C removes the inhibitory phosphorylation sites Thr14 and Thr15 from CDK1, activating it and directing tumor cells into mitosis." (PMID 39949984, 2025). "Further, we explored how the CDK1 gene affects the infiltration pattern of tumor immune cells and its potential impact on therapeutic efficacy." (PMID 39991589, 2025). "Compound 17, which exhibited cytotoxicity against PANC−1 cells, was linked to 55 targets, including key targets such as EGFR, AKT1, CDK1, CDK2, MMP9, PIK3CG, and TERT, closely associated with tumour cell proliferation, migration, and apoptosis." (PMID 41006588, 2025). "By analyzing the relationship between CDK1 expression and tumor-infiltrating lymphocytes (TILs), researchers can more accurately predict patients’ responses to immunotherapy, thus achieving more accurate individualized immunotherapy." (PMID 40332418, 2025). "CDK1 stood out as a candidate target to relieve CTSG's tumor-killing function in the pooled genome-wide CRISPR/Cas9 screening." (PMID 41040318, 2025). "In most tumor cells, dinaciclib blocks cell growth primarily by inhibiting CDK1 and CDK2 and promotes apoptosis by suppressing RB phosphorylation." (PMID 39800748, 2025). "Research has revealed that tumor cells with high MYC expression exhibit enhanced dependence on CDK1." (PMID 38638876, 2024). "The results indicate a heterogeneous expression pattern of Cdk1/2/5/9, as well as various differentiation tumor markers in BTC cells." (PMID 39668430, 2024). "For example, CDK1 can influence tumor immunity by regulating the migration of immune cells into the bladder cancer microenvironment." (PMID 39445019, 2024).
tumor (continued). "CDK1 is an important factor in the cell cycle control system, and increased CDK1 activity is common in tumor cells." (PMID 38967843, 2024). "Studies in breast cancer have revealed elevated CDK1/2 levels in approximately 60% of tumor samples compared to normal breast tissue." (PMID 38606093, 2024). "Further analysis highlighted four specific hub genes—CCNA2, CCNB2, CDK1, and TOP2A—that showed significantly higher expression in HBV‐associated HCC tumor samples compared to normal samples in the GEPIA database." (PMID 38895552, 2024). "High mRNA expression of CDK1, PCNA, EZH2, BUB1, and CXCR4 in tumor was significantly associated with lower RFS." (PMID 38831458, 2024). "IHC staining exhibited a reduced CDK1 level and an increased level of the apoptosis marker cleaved caspase-3 in tumours from the KO group compared to those in the WT group." (PMID 39180763, 2024). "CDK1 is highly expressed in tumor cells, where it promotes cell proliferation by regulating the G2/M phase to induce epithelial-to-mesenchymal transformation." (PMID 38243250, 2024). "CircRNA circ-Ccnb1, derived from the cell proliferation-related gene Ccnb1, can form a triplet complex with Ccnb1 and CDK1, block the function of Ccnb1 and CDK1, and inhibit the activities of tumor cells." (PMID 39199340, 2024). "To investigate how PKMYT1 and ATR inhibition are cooperating to activate CDK1, we measured levels of the CDK1 inhibitory phosphorylation at Thr14 (CDK1-pT14) in cell lines and tumor xenografts." (PMID 38410486, 2024). "This suggests a potential avenue for genetic modifications supporting tumor growth through increased CDK1/Cyclin B activity." (PMID 38576486, 2024). "Our previous data showed that SHCBP1 knockdown led to early M-phase entry by downregulating WEE1 expression and subsequently reducing CDK1 phosphorylation at Tyr15, resulting in the abrogation of the G2–M checkpoint in tumour cells." (PMID 38365687, 2024). "In all 16 pairs of clinical samples, the circCDK1:CDK1 mRNA ratio was lower in the ccRCC tumour tissues than in the para-ccRCC tissues." (PMID 39180763, 2024). "This underpins the functional linkage between UBE2C and CDK1, substantiated by their correlated expression in tumor tissues." (PMID 39033780, 2024). "Among drug hits identified through in vitro screens data, we also spotted Aurora kinase and Cdk1 inhibitors, which halt cell cycle progression of tumour cells at the checkpoint, resulting in G2/M phase cell cycle arrest." (PMID 38396175, 2024). "CDK1 is a cell-cycle gene that is up-regulated in HCC tumours and was one of the AP genes in our analysis." (PMID 36737737, 2023). "Our studies using clinical samples support that upregulation of ODF2L in primary EOC cells positively correlates with CDK1 inactivation and cell viability in vitro and predicts xenografted tumor growth in vivo under AZD1775 treatment." (PMID 36378528, 2023). "The in vitro and in vivo models showed that genetic and pharmacological blockade of CDK1 restored the anti‐tumor effect of oxaliplatin." (PMID 37428466, 2023). "Targeting CDK1 by RO-3306 inhibited cell proliferation, induced cellular stress, and apoptosis, reduced invasive capacity, and reduced tumor growth in OC cells and a transgenic mouse model of OC." (PMID 37569750, 2023). "The CDK1/stroma cluster cells, macrophages, and T cells shared a unique communication pattern, and the CDK1/tumor cluster cells, tumor cells, and epithelial cells exhibited a unique signature." (PMID 36950551, 2023). "CDK1 was consistently up-regulated across most of the patients, with a clear distinction between the expression values in tumour and adjacent normal samples (top)." (PMID 36737737, 2023). "Clinical trials targeting CDK1, the key enzyme in the process of tumor proliferation, to induce cell cycle arrest are being carried out extensively." (PMID 37081889, 2023). "A recent study reported that tumor initiation in human melanoma was promoted by CDK1-mediated SOX2 interactions." (PMID 37620336, 2023).
tumor (continued). "As a major member of the CDK family, CDK1 plays a dominant role in tumor initiation and stemness maintenance." (PMID 37743465, 2023). "CDK1 was mostly expressed in the 4, 9, 11 and 23 clusters, which were primarily tumor cells and macrophages." (PMID 36950551, 2023). "It has been demonstrated that not only does CDK1 regulate the cell cycle, but it also plays a part in tumor cell proliferation." (PMID 37457582, 2023). "PIN1 and CDK1 cooperatively modulate the protein turnover of pVHL, thereby conferring tumor growth, chemotherapeutic resistance and metastasis both in vitro and in vivo." (PMID 36813923, 2023). "Further exploration led to the identification and validation of CDK1, CCNB1, AURKA, EZH2, and CCNA2, a five-gene signature with high interactions and potentially associated with tumor stemness, hypoxia enhancement, and TME regulation." (PMID 37189841, 2023). "As a serine/threonine protein kinase, CDK1 is reported to phosphorylate a number of substrates, including both tumor promotors and tumor suppressors." (PMID 37311884, 2023). "CDK4/6 inhibitors inhibit the CDK1-Cyclin D4 complex, which induces cell cycle arrest in the G1 phase and apoptosis in some tumor cells." (PMID 37305685, 2023). "As a key regulator of the cell cycle, the mRNA expression of CDK1 has been found to be up-regulated in a variety of tumor tissues, including ACC, and high expression of the gene was associated with poor prognosis in patients." (PMID 38053725, 2023). "Conversely, AIM2 knockdown decreased CDK1 expression, tumor cell invasion, and metastatic potential, and inhibited the growth and angiogenesis of metastatic tumor cells." (PMID 37497237, 2023). "RO-3306 is a selective, ATP-competitive, and cell-permeable CDK1 inhibitor that shows potent anti-tumor activity in multiple pre-clinical models." (PMID 37569750, 2023). "Given its high selectivity and specificity for CDK1, this current study used RO-3306 to address the anti-tumor potential of CDK1 inhibition in OC cell lines and a transgenic mouse model of OC." (PMID 37569750, 2023). "Silencing CDK1 or STAT3 suppressed tumor stemness properties, while overexpressing CDK1 or STAT3 showed the opposite effect." (PMID 37743465, 2023). "The CDK1-dependent phosphorylation of human telomerase reverse transcriptase promotes tumor growth in a telomere-independent manner." (PMID 38143739, 2023). "Much research has shown that dysregulation of CDK1 results in more aggressive tumor development, increased cell proliferation, and chromosomal instability." (PMID 37511023, 2023). "Our studies further demonstrated the effect of CDK1 in the maintenance of tumor stemness by mediating the phosphorylation of the important transcription factor STAT3." (PMID 37743465, 2023). "According to the cell types in which CDK1 was expressed, we classified the CDK1-expressing clusters into two subgroups, the CDK1/tumor cluster and the CDK1/stroma cluster." (PMID 36950551, 2023). "The analysis showed that CDK1 promoted tumor cell proliferation mainly through “gain” CNVs, which also negatively regulated the infiltration of multiple immune cells, including B cells, CD4+ T cells, and dendritic cells." (PMID 36950551, 2023). "Several molecules enhance tumor cell growth, migration, or invasion by upregulating the expression of CDK1 in different ways." (PMID 37311884, 2023). "We also demonstrated that the SE-lncRNA LINC00880 is dependent on pT161-CDK1 for promoting tumor progression, which provides a new perspective from which to achieve the specific activation of CDK1 without affecting its expression." (PMID 37620336, 2023). "Recent studies have revealed that CDK1 plays an important role in tumor initiation and stem cell pluripotency." (PMID 37743465, 2023). "Our results demonstrated that PIN1 and CDK1 cooperatively destabilize pVHL, thereby promoting tumor progression of TNBC." (PMID 36813923, 2023).